PPP1R2P1 (protein phosphatase 1 regulatory inhibitor subunit 2 pseudogene 1)
Description:
Inhibitor of protein-phosphatase 1.
Synonyms: IPP-2P; formerly PPP1R2P
Gene: Transcribed processed pseudogene on chromosome 6 (32,879,216 to 32,879,833, reverse strand). Ensembl gene ENSG00000234515.
Diseases named in the same sentence as PPP1R2P1 in open-access papers:
PPP1R2P1 is named in the same sentence as 2 diseases in open-access papers, as found by Europe PMC text mining. Sharing a sentence is not in itself a finding about the gene and the disease. The quoted sentences say what the papers report.
kidney disorder (1 paper, 2019). A disease involving the kidney. "Our results also revealed a significant correlation between PPP1R2P1 (A/G) and albumin/globulin ratio, which is an indicator of liver and kidney disorders." (PMID 31827636, 2019).
PPP1R2P1 also shares sentences with these, for which no sentence is quoted: polycythemia (1 paper).